CCL21 (C-C motif chemokine ligand 21)
Diseases named in the same sentence as CCL21 in open-access papers (continued):
Sharing a sentence is not in itself a finding about the gene and the disease.
unstable angina (1 paper, 2012). "Interestingly, increased levels of CCL19 and CCL21 in atherosclerotic plaques have been found in stable and unstable angina." (PMID 23077561, 2012).
Ureteral obstruction (1 paper, 2010). Obstruction of the flow of urine through the ureter. "Moreover, CCR7-positive fibrocytes migrate into the kidney in response to SLC/CCL21 and contribute to kidney fibrosis induced by unilateral ureteral obstruction in mice." (PMID 20126461, 2010).
uveal melanoma (1 paper, 2023). A melanoma derived from melanocytes of the uveal tract. "The presented data on CCL21 and TLS-like regions in uveal melanoma is thus hypothesis generating and warrants further examination in future clinical and experimental studies." (PMID 37377898, 2023).
WHIM syndrome (1 paper, 2011). "However, the experimental systems (i.e. cells expressing transfected mutant receptors; chemokine CCL21 that desensitizes its receptor CCR7 at low level; leukocytes from WHIM syndrome patients)." (PMID 21559528, 2011).
tumor (422 papers, 2006 to 2026). "Conversely, changes in the expression of CCL2, CCL5, and CCL21 were linked to tumor stages, influencing tumor growth and metastasis by modulating immune cell activity, thereby highlighting their value as therapeutic targets." (PMID 39859340, 2025). "Simultaneously, we revealed CCR7 expression in stromal cells, with increased infiltration of CCR7+ immune cells into the tumor mesenchyme associated with high CCL21 expression at tumor sites." (PMID 40685403, 2025). "Such tumor-induced remodeling of FRCs, in particular, reduced CCL21 expression, is associated with perturbed lymphocyte compartmentalization and proliferation, while dampened IL-7 production is associated with reduced T cell numbers." (PMID 38038708, 2024). "Mechanistically, the loss of mACKR4 leads to increased intra-tumor CCL21 levels and elevated numbers of CD103+ DCs and CD8+ cells within tumors." (PMID 39290345, 2024). "We discovered a deficiency of highly expressed chemokine factor CAF_CCL21 in the tumor microenvironment of PD patients." (PMID 38505619, 2024). "CCL19 and CCL21 also influence lymphocyte migration through high endothelial venules (HEVs), which are critical in tumor immunosurveillance and are linked to the overexpression of lymphoid chemokines and genes related to Th1 and naïve T cells." (PMID 39766071, 2024). "Mounting evidence suggests that tumour‐associated CCR7 expression mediates migration towards CCL21‐expressing lymphoid organs." (PMID 37170733, 2023). "Depletion of CD4+ and/or CD8+ immune cells in mice using specific antibodies confirmed that the inhibitory effect of CCL21 on tumor growth was associated with specific T cell chemoattraction." (PMID 37185750, 2023). "Lymphatic function pre-tumor was significanlty correlated with tumor size at eight weeks and was associated with increased infiltration by cells expressing the lymphatic trafficking ligand CCL21." (PMID 37801190, 2023). "The targeted migration of activated tumor-specific T cells is associated with Chemokine ligand 21 (CCL21) and Intercellular adhesion molecules 1 (ICAM-1)." (PMID 36761748, 2023). "The expression of VEGF-C in the tumor microenvironment recruits CCL21 expressing cells and naïve T cells, and tumor associated lymphatic vessels express PD-L1, which leads to an immunosuppressive environment." (PMID 36158182, 2022). "Another chemokine that has been linked to EGFR signalling is CCL21, previously shown to be involved in the recruitment and infiltration of tumour-specific T-cells into the TME." (PMID 36010935, 2022). "In agreement, total RNAs from skin biopsies of epidermis versus those from involved dermis of MF associated the presence of tumor cells in the dermis with the CCR7/CCL21 axis." (PMID 34778050, 2021). "Although FRC growth or loss seems tumor specific, most data show that FRCs are reprogrammed by tumor cells to influence normal immune cell composition in TDLNs, and that CCL21 and IL-7 are critical to these changes." (PMID 33808959, 2021). "In our study, CCL21 was down-regulated in BC, and high levels of CCL21 was associated with negative PR, triple-negative subtype and basal-like subtype and low tumor grade." (PMID 33146700, 2020). "CCL21 was down-regulated in BC, while high levels of CCL21 was associated with negative PR, triple-negative subtype, basal-like subtype and low tumor grade." (PMID 33146700, 2020). "Increasingly more findings have demonstrated that the cross-talk of CC chemokines, including CCL8 and CCL21, in BC is significantly associated with carcinogenesis, tumor metastasis and chemoresistance." (PMID 33146700, 2020).
tumor (continued). "We identified a panel of tumor-associated genes that were either significantly upregulated or downregulated by more than 2-fold in CCL21-overexpressing PANC-1 cells in our DNA microarray analysis." (PMID 29687228, 2020). "Overexpression of CCL21 in tumor cells induce a tolerogenic microenvironment associated with a production of Transforming Growth Factor-β (TGF-β) that favors the recruitment of regulatory T cells (Tregs) and myeloid deriving suppressor cells (MDSC)." (PMID 30420855, 2018). "This shows the involvement of the same CCL21/CCR7 axis in the tumor cell to cancer associated fibroblast recognition." (PMID 28416768, 2017). "Lymphatic invasion by CCR7 expressing pancreatic ductal adenocarcinoma (PDAC) cells is additionally enhanced by upregulation of CCL21 in tumor-associated lymphatics." (PMID 28036019, 2016). "In prostate cancer, hypoxia-preconditioned MSCs produce CCL21 to attract tumor cells expressing CCR7 which is associated with enhanced lymph node metastasis of the tumor." (PMID 25110692, 2014). "Two murine studies used adenoviral vectors to express CCL21 in DC populations and both reported that increased CCL21 levels caused an increase in lymphocyte migration to tumor." (PMID 24762633, 2014). "Another study not only introduced CCL21 gene-encoding plasmid (pAAV-IRES-hrGFP/SLC) into bone marrow-derived DCs but also pulsed DCs with whole tumor lysate and then injected the construct into tumor-bearing mice with similar efficacy." (PMID 24967094, 2013). "This suggested that the specific loss of Ndst1 in the lymphatic endothelium reduced not only lymph node metastasis, but also the ability of CCL21 to associate with tumor cells in the lymph node sections." (PMID 21172016, 2010). "Initially, mutant (Ndst1f/fTekCre+) mice showed not only a reduction in LLC metastasis to regional lymph nodes, but also a reduction in CCL21 associated with metastatic tumor colonies." (PMID 21172016, 2010). "Lymph node - colonizing tumor deposits in wildtype littermates were associated with abundant CCL21 that localized with the tumor deposits." (PMID 21172016, 2010). "Pre-tumor lymphatic pulsing was associated with tumor volume at 8 weeks (P = 0.02) and was significantly correlated with expression of the lymphatic tracking ligand CCL21 (P = 0.05)." (PMID 37801190, 2023). "CCL19 or CCL21 produced by tumor cells is associated with tumor invasion and immune tolerance." (PMID 34689225, 2022). "Besides, the cDC3_LAMP3 cells that highly expressed LAMP3, IDO1, and CCL21 associated with high maturation and migration ability were also considered as tumor-promoting immune cells." (PMID 35087839, 2021). "Future studies could be performed on smaller tumors despite the risk of leakage from tumor target given the revealed safety profile of CCL21 dendritic cell injections in our study." (PMID 34806054, 2021). "Results of GO enrichment analysis and KEGG pathways revealed that CCL8 and CCL21 mainly function in chemokine signaling pathway, G protein-coupled receptor and inflammatory response, which are associated with BC carcinogenesis, tumor immune escape and chemoresistance." (PMID 33146700, 2020). "Increased expression of CCL21 might be associated with an increase in the number of dendritic cells or an improved immunologic response upon tumor cell death." (PMID 27369431, 2016). "In cell-based studies, we investigate mechanisms that may underlie these findings, and show that CCL21-dependent tumor cell migration toward lymphatic endothelium critically depends upon lymphatic HS." (PMID 21172016, 2010). "However, in Cre+ mutants, pan-keratin positive tumor patches were markedly reduced (graph and photomicrographs), and detectable tumor deposits were characterized by minimal associated CCL21 immunoreactivity (bottom row)." (PMID 21172016, 2010). "However, CCL21 immunoreactivity associated with the limited tumor deposits found in mutant lymph nodes was reduced." (PMID 21172016, 2010).
tumor (continued). "Furthermore, a phase 1 clinical trial of immunotherapy discovered that administering DCs expressing the CCR7 receptor ligand CCL21 into lung cancers could enhance immunity and cause the tumor to shrink." (PMID 36874133, 2023). "Innate immune cells, such as mature dendritic cells and M1-tumor-associated macrophages (TAM), produce cytokines (IFN-α, IL-12, IL-18, or TNF-α) and chemokines (CXCL9, CXCL10, or CCL21) that suppress tumor angiogenesis." (PMID 41373757, 2025). "For instance, cytokines such as IL-12 enhance T-cell activity, while chemokines like CCL19 and CCL21 promote dendritic cell migration to the tumor site." (PMID 39861713, 2025). "LIGHT/TNFSF14, a lymphotoxin-related cytokine, has recently emerged for its role in the promotion of TLS-like aggregates with HEVs in vivo via the induction of CCL21 secreted by tumor endothelial cells, thus increasing the influx of T and B cells." (PMID 40319321, 2025). "CC chemokines such as CCL1, CCL2, CCL3, CCL21 and CCL25 are also associated with invasion and migration in many tumours." (PMID 40852716, 2025). "Tumor cells are chemotactically recruited to lymphatic vessels by factors like CCL21, entering the lymphatic circulation.Lymph nodes act as “filters” to trap circulating tumor cells, forming metastatic foci." (PMID 40421086, 2025). "Previously, intratumoral administration of murine dendritic cells genetically modified to express CCL21 led to significant tumor response in a murine lung cancer model." (PMID 40006675, 2025). "Marine polysaccharide systems address this by delivering chemokines (e.g., CCL21) to attract T cells and NK cells to tumor sites, while fucoidan-based magnetic nanomedicines revitalize tumor-infiltrating lymphocytes to repair the immunosuppressive TME." (PMID 41149588, 2025). "The increased migration and survival of immune cells in the tumor microenvironment (TME), driven by CCL19 and CCL21, are linked to improved therapeutic outcomes, especially when combined with immunotherapies." (PMID 39861713, 2025). "In summary, our research conclusively demonstrates that CCR7 and ERK1/2 serve as crucial prognostic markers in DLBCL, with their interaction via the CCL21 pathway playing a pivotal role in tumor progression by activating ERK1/2." (PMID 39735670, 2025). "Based on these clinical values of TLS, we can directly inject specific cytokines (such as CXCL13 and CCL21) into the tumor to promote immune cell infiltration, TLS formation, and tumor shrinkage." (PMID 40612858, 2025). "Other studies have also demonstrated that the co-expression of IL-7 with CCL21 or CCL9 on CAR-T cells boosts their anti-tumor capabilities." (PMID 41450878, 2025). "CCR7 interacts with its ligand CCL21, which is found at higher levels in the extracellular matrix of tumor lesions." (PMID 40861461, 2025). "In these scenarios, tumor cells often exhibit CCR7 positivity alongside increased extracellular matrix levels of CCL21, supporting enhanced migratory capacity mediated via the PI3K/Akt and mTOR signaling pathways." (PMID 40861461, 2025). "Studies suggest that when tumour cells express CCL21, an anti-tumourigenic effect occurs through the inhibition of angiogenesis and increased recruitment of CD8+ T cells and dendritic cells." (PMID 40852716, 2025). "Preclinical and early-phase clinical studies further show that CCL21-DCs tumor-lysate vaccines can augment anti-PD-1 activity, underscoring the broader potential of modulating TLS-associated chemokines." (PMID 41374956, 2025). "CCL19 and CCL21 recruit naïve/central memory T cells to tumor tissue, allowing them to migrate from the HEVs into the TLS." (PMID 40038799, 2025). "It is possible the increased CCL21 gene expression in the tumor and CCL21 protein content in the axillary lymph node are reflective of enhanced lymphatic capillary immune functionality within one to three days after SA-HFIRE, respectively." (PMID 39998766, 2025).
tumor (continued). "The relative RNA expression demonstrated that Ccl5, Ccl8, Cxcl9, Cxcl10, Cxcl13 and Ccl21 were significantly higher in the 4MOSC1 tumours following oHSV therapy." (PMID 39219056, 2025). "The CCL21 protein content significantly correlates with the CCL21 gene expression measured in the tumor." (PMID 39998766, 2025). "CCL21, with the ability to promote tumor metastasis and tumor cells‐derived EVs, containing GM‐CSF mRNA with the antitumor ability and sonosensitizer Chlorin e6 (Ce6), were added in hydrogels." (PMID 41476648, 2025). "The CCR7-CCL19/CCL21 axis also orchestrates the migration of antigen-carrying DCs from the tumor to the DLNs41,43,44." (PMID 38951172, 2024). "CD93-blocking antibodies (anti-CD93) inhibit lung tumor growth better than VEGF receptor-blocking antibodies because anti-CD93 inhibit tumor angiogenesis and promote CCL21 secretion from pMCs." (PMID 38250037, 2024). "To further confirm the role of CCL21, we utilized an in vitro stimulation assay where both pDCs and mDCs were treated by CCL21 or tumor cell co-culture for 24 h." (PMID 39456552, 2024). "Our results showed that M057 stimulated anti-lung tumor immunity via CCL21 and normalized tumor vasculature, thus exhibiting more robust efficacy than anti-VEGFR." (PMID 38250037, 2024). "We examined if CCL21-induced pDCs suppress anti-tumor immunity via Tregs; however, using co-culture of CCL21-induced pDCs with naïve CD4 T cells, neither Treg lineage induction nor Treg proliferation was observed." (PMID 39456552, 2024). "So, we used CCL21 or CCR7 antibodies to block the migration of pDCs in response to CCL21 protein or tumor co-culture conditions." (PMID 39456552, 2024). "To further examine the future therapeutic potential of antibody-mediated targeting of CCL21 to decrease pDC tumor infiltration, we examined the effect of CCL21 blockade in vivo on pDC migration and activation." (PMID 39456552, 2024). "Taken together, all these data suggest that CCL21-induced pDCs show a regulatory phenotype that contributes to the tumor immunosuppressive microenvironment." (PMID 39456552, 2024). "Engineered CAR-T cells co-expressing IL-7 and CCL21 exhibited increased anti-tumor efficacy due to significantly improved survival and infiltration of both the CAR-T cells and DCs in the TME." (PMID 39076974, 2024). "Hypoxic TAMs, induced by the tumor, secrete chemokine ligand-21 (CCL21), which attracts and suppresses NKTs." (PMID 39588373, 2024). "Western blot analysis of nuclear and cytoplasm fractions indicated that the concentration of β-arrestin and CIITA in the nucleus was increased by about 50% in pDCs after CCL21 treatment or tumor cells co-culture." (PMID 39456552, 2024). "The RNA sequencing database from a GBM patient cohort (156 patients, four non-tumor controls) showed a trend toward upregulated expression of CCL21 (p = 0.22)." (PMID 39456552, 2024). "Chemokine C‐C motif ligand 21 (CCL21) was screened by transcriptomic analysis in tumor tissues from HCC patients with different responses to ICIs." (PMID 38367070, 2024). "It has been suggested that CCR7 plays binary roles in cancer; the overexpression of the CCR7/CCL21 axis is associated with lymph node metastasis of various cancer types, and at the same time, CCR7 tends to potentiate immune cell movement to tumours." (PMID 38256152, 2024). "A preclinical study and a phase I clinical trial of in situ administrated DCs, which were genetically modified to overexpress CCL21 (CCL21-DC), demonstrated increased tumor antigen presentation, leading to systemic antitumor immunity." (PMID 38911455, 2024). "Neutrophils in vitro and HCC subcutaneous tumor model in vivo were applied to explore the role of CCL21 on the tumor microenvironment (TME) of HCC." (PMID 38367070, 2024). "We observed a statistically significant upregulation of CCL21 expression in the tumor tissues of HCC patients that responded to immunotherapy." (PMID 38367070, 2024).